NUFIP1P1 (NUFIP1 pseudogene 1)
Synonyms: formerly NUFIP1P
Gene: Processed pseudogene on chromosome 6 (66,093,431 to 66,094,909, reverse strand). Ensembl gene ENSG00000218890.
Diseases named in the same sentence as NUFIP1P1 in open-access papers:
NUFIP1P1 is named in the same sentence as 1 disease in open-access papers, as found by Europe PMC text mining. Sharing a sentence is not in itself a finding about the gene and the disease.
NUFIP1P1 shares sentences with these, for which no sentence is quoted: glioblastoma (1 paper).